WASHC1 (WASH complex subunit 1)
Description:
Acts as a component of the WASH core complex that functions as a nucleation-promoting factor (NPF) at the surface of endosomes, where it recruits and activates the Arp2/3 complex to induce actin polymerization, playing a key role in the fission of tubules that serve as transport intermediates during endosome sorting. Involved in endocytic trafficking of EGF (By similarity). Involved in transferrin receptor recycling. Regulates the trafficking of endosomal alpha5beta1 integrin to the plasma membrane and involved in invasive cell migration. In T-cells involved in endosome-to-membrane recycling of receptors including T-cell receptor (TCR), CD28 and ITGAL; proposed to be implicated in T cell proliferation and effector function. In dendritic cells involved in endosome-to-membrane recycling of major histocompatibility complex (MHC) class II probably involving retromer and subsequently allowing antigen sampling, loading and presentation during T-cell activation (By similarity). Involved in Arp2/3 complex-dependent actin assembly driving Salmonella typhimurium invasion independent of ruffling. Involved in the exocytosis of MMP14 leading to matrix remodeling during invasive migration and implicating late endosome-to-plasma membrane tubular connections and cooperation with the exocyst complex. Involved in negative regulation of autophagy independently from its role in endosomal sorting by inhibiting BECN1 ubiquitination to inactivate PIK3C3/Vps34 activity (By similarity). (Microbial infection) Nucleation-promoting factor that plays a major role in human papillomavirus infection by facilitating branched actin-driven scission in endocytosis.
Synonyms: FAM39E; WASH1; FLJ00038; WASH
Tractability: PROTAC: UniProt records ubiquitination sites on it; ubiquitination databases record sites on it.
Gene: Protein-coding gene on chromosome 9 (14,475 to 73,865, reverse strand). Ensembl gene ENSG00000181404.
Subcellular location: Early endosome membrane; Recycling endosome membrane; Late endosome; Cytoplasmic vesicle, autophagosome; Cytoplasm, cytoskeleton, microtubule organizing center, centrosome, centriole
Subcellular location (Human Protein Atlas): Vesicles
Gene Ontology:
Molecular function: alpha-tubulin binding; protein binding; ubiquitin protein ligase binding; phosphatidylinositol 3-kinase inhibitor activity
Biological process: Arp2/3 complex-mediated actin nucleation; endocytic recycling; exocytosis; extracellular matrix disassembly; positive regulation of cell migration; positive regulation of pseudopodium assembly; retrograde transport, endosome to Golgi; endosomal transport; negative regulation of autophagy; regulation of Arp2/3 complex-mediated actin nucleation; regulation of protein ubiquitination
Cellular component: early endosome; exocyst; late endosome; WASH complex; autophagosome; early endosome membrane; recycling endosome; recycling endosome membrane; centriole; cytosol
Genetic constraint (gnomAD): Loss-of-function variants: 8 observed, 5.05 expected, observed/expected ratio (o/e) 1.59, 90% interval 0.86 to 1.94. That is too few expected variants to judge how well the gene tolerates losing a copy. Missense variants: 69 observed, 61.93 expected, observed/expected ratio (o/e) 1.11, 90% interval 0.92 to 1.36. Synonymous variants: 28 observed, 27.06 expected, observed/expected ratio (o/e) 1.03, 90% interval 0.77 to 1.42.
Homologues: Orthologues: macaque WASHC1 (95% identical), dog WASHC1 (90% identical), pig WASHC1 (87% identical), mouse Washc1 (84% identical), rat Washc1 (83% identical), tropical clawed frog washc1 (69% identical), zebrafish wash1 (66% identical), Drosophila melanogaster wash (33% identical), Caenorhabditis elegans ddl-2 (29% identical). Paralogues in human: WASH6P (90% identical).
Diseases named in the same sentence as WASHC1 in open-access papers:
WASHC1 is named in the same sentence as 5 diseases in open-access papers, as found by Europe PMC text mining. Sharing a sentence is not in itself a finding about the gene and the disease. The quoted sentences say what the papers report.
Ritscher-Schinzel syndrome (1 paper, 2021). "Diseases associated with WASHC1 include Wiskott-Aldrich Syndrome and Ritscher-Schinzel Syndrome." (PMID 34465353, 2021).
WASHC1 also shares sentences with these, for which no sentence is quoted: tumor (2 papers); liver cirrhosis (1); neuroblastoma (1); Wiskott-Aldrich syndrome (1).